CSF1R (colony stimulating factor 1 receptor)
Diseases named in the same sentence as CSF1R in open-access papers (continued):
Sharing a sentence is not in itself a finding about the gene and the disease.
breast cancer (continued). "To further confirm the direct effect of mcr84 on myeloid cell PD-L1 expression in vivo, we implanted F246-6 breast cancer cell line in Flk-1fl/fl or Csf1r-Cre+Flk-1fl/fl mice." (PMID 34673569, 2021). "Previously, limited studies have reported the prognostic impact of CSF-1R expression in human breast cancers, and the significance of its expression on tumor-associated macrophages in clinical breast cancer specimens is not known." (PMID 34830923, 2021). "Although the binding of IL-34 to CSF1R modulates several cancer-driving signaling pathways, little is known about the role of IL-34/CSF1R signaling in breast cancer." (PMID 33800170, 2021). "These promising preclinical experiments led to clinical targeting of either M-CSF or CSF1R in patients with advanced breast cancer." (PMID 34832904, 2021). "Macrophage depletion with clodronate liposomes and colony-stimulating factor 1 receptor (CSF1R) reduces breast cancer cell growth in the bone." (PMID 34745140, 2021). "Previously, few studies have investigated CSF-1R expression in clinical samples showing prognostic relevance with regards to ipsilateral breast cancer recurrence and nodal involvement." (PMID 34830923, 2021). "In this study, we investigated CSF-1R protein expression on breast cancer cells and macrophages and their relationship with other immune cells and breast cancer survival." (PMID 34830923, 2021). "Trans-(−)-kusunokinin, an anticancer compound, binds CSF1R with low affinity in breast cancer cells." (PMID 34361688, 2021). "In another study, CSF1R was inhibited with a blocking antibody in pre-malignant MMTV-HER2 tumors that model HER2+ breast cancer." (PMID 34832904, 2021). "Efficient targeting of TAM using small molecule CSF-1R inhibitors was assessed in many tumour models, including solid tumours and breast cancers." (PMID 34950148, 2021). "Pexidartinib is another inhibitor of CSF1R that is used in combination with a microtubule inhibitor (Eribulin) for breast cancer patients." (PMID 33747948, 2021). "First, for some recurrent mutations, such as those from CTNNB1, CSF1R, JAK2, HRAS, and RUNX1, an exhaustive literature search showed that the clinical significance in breast carcinoma has rarely been addressed." (PMID 34203389, 2021). "They concluded that the cytostatic effects of this molecule in breast cancer cells relied on its ability to suppress the colony stimulating factor-1 receptor (CSF1R), whose downregulation then affected Akt and its downstream molecules cyclin D1 and CDK1." (PMID 33256185, 2020). "Targeting CSF1R by imatinib or AFS98 inhibits bone metastases in breast cancer by suppressing osteoclasts." (PMID 32801364, 2020). "It shows the ability to inhibit CSF1R, and through its inhibition of the CSF1R, it is currently used as the treatment of patients with glioblastoma, breast cancer, and other cancers in clinical." (PMID 32161718, 2020). "We confirmed the primary immunotherapeutic effects of the CSF1R inhibitor in the MMTV-PyMT mammary tumor models by demonstrating that the drug achieves reduction in macrophage accumulation together with tumor growth inhibition." (PMID 30696910, 2019). "In a recent study using a transgenic mouse model with breast cancer cells, Salvagno and colleagues showed that CSF-1R blockade is an effective way to enhance CDDP-induced anticancer activity, which is stimulated by an intratumoral type I IFN response." (PMID 31450627, 2019). "Clinical trials combining the use of CSF1-R inhibitors and chemotherapy have been initiated for the treatment of various cancers based on initial preclinical data in mouse breast cancer models where a CSF1R blockade increased the efficiency of paclitaxel." (PMID 30853982, 2019). "Another study revealed that pharmacological blockade of CSF-1/CSF-1R targeted specifically breast cancer CD11b+ Ly6Gneg Ly6Clow F4/80+ TAMs and induced increase in CD8+ lymphocyte infiltration." (PMID 31331034, 2019).
breast cancer (continued). "To then further establish these TAM iron deposits as immunotherapy targets, we initiated preclinical CSF1R (colony-stimulating factor-1 receptor) inhibitor (BLZ945) trials in murine breast cancer models." (PMID 30696910, 2019). "We also confirmed that the iron+ macrophages express CSF1R in murine and human breast cancers supporting their role as targets of these immunotherapies." (PMID 30696910, 2019). "We therefore focused on the CSF-1/CSF-1R axis and next studied the expression of CSF-1 at the transcriptional and protein levels in a panel of breast cancer cells." (PMID 29930294, 2018). "Characterization of macrophage phenotypes in breast cancer subtypes using CIBERSORT_LM22 values and the TCIA database showed, as expected, that CSF-1/CSF-1R expression was positively associated with macrophages in all subtypes in the analyzed dataset." (PMID 29796177, 2018). "Together with our in vitro experiments these findings suggest that CSF-1R-independent actions of IL-34 via PTPRZ1 should be considered in evaluating IL-34 roles in breast cancer subtypes." (PMID 29796177, 2018). "Analysis of CSF-1 and CSF-1R expression in molecular breast cancer subtypes revealed generally lower levels for both when compared to normal tissue." (PMID 29796177, 2018). "By comparing stromal, immune and ESTIMATE scores in intrinsic breast cancer subtypes, we identified strong relationships of CSF-1 and CSF-1R to all scores." (PMID 29796177, 2018). "Our previous breast cancer studies found that CSF-1/CSF-1R signaling promotes tumor growth and it has been demonstrated that CSF-1R blockade using antibodies reduced the number of resident tumor-associated macrophages (TAMs) in tumors." (PMID 29796177, 2018). "Anti-CSF-1R agents have been shown to be effective against recruitment of M2-like macrophages in breast cancer models, and anti-CSF1R inhibitors used in combination with paclitaxel decreased tumor growth and pulmonary metastasis." (PMID 30356656, 2018). "CSF1 is required for survival of immunosuppressive TAMs that promote angiogenesis and tumor metastasis and studies in mouse models of breast cancer have shown TAM recruitment into the tumor due to CSF-1/CSF-1R signaling." (PMID 29862083, 2018). "Blockade of CSF-1 and CSF-1R in combination with chemotherapy improved survival and reduced the metastatic frequency in a breast cancer model and this response correlated with an increase in cytotoxic CD8+ T cells within the tumours." (PMID 28210073, 2017). "Preclinical evidence also supports the potential of CSF1R inhibition in breast cancer in conjunction with conventional chemotherapy." (PMID 27959923, 2016). "Ectopic expression of CSF-1R was shown to convey pro-tumorigenic properties, to breast cancer and mesothelioma cells." (PMID 27486763, 2016). "Moreover, because mammary tumor microenvironment is rich in tumor-associated macrophages, which express CSF-1R (they have resident-type macrophage phenotype), this approach could also affect tumor-associated macrophages that are an important element in cancer development and invasion." (PMID 23561040, 2013). "It suggests that CSF-1R can be even more important for canine mammary cancer development than for breast cancer." (PMID 23561040, 2013). "This study was therefore designed to characterize the role of CSF-1R in canine mammary cancer cells proliferation, apoptosis, migration, and invasion." (PMID 23561040, 2013). "Our own results also confirm these findings, as we observed the highest expression of CSF-1R in the most malignant and metastatic mammary tumors." (PMID 23561040, 2013). "The wide expression of the CSF-1/CSF-1R pair across breast cancer cell subtypes supports CSF-1/CSF-1R targeting in breast cancer therapy." (PMID 22096574, 2011). "We also demonstrate that c-Jun, cyclin D1 and c-Myc, known for their involvement in cell proliferation, are downstream CSF-1R in breast cancer cells." (PMID 22096574, 2011).
breast cancer (continued). "We found ERK1/2, c-Jun, cyclin D1 and c-Myc, known for their involvement in cell proliferation, to be downstream CSF-1R in breast cancer cells." (PMID 22096574, 2011). "In this work, we characterized the role of CSF-1R in the proliferation of breast cancer cells and found that CSF-1R is widely expressed in breast cancer cell lines at both mRNA and protein levels." (PMID 22096574, 2011). "Elucidation of the involvement of CSF-1R in breast cancer cell proliferation would strengthen the rationale of CSF-1R targeting in CSF-1R expressing cancers." (PMID 22096574, 2011). "To further characterize CSF-1R involvement in breast cancer cell proliferation we treated breast cancer cells with CSF-1R siRNA." (PMID 22096574, 2011). "In the present study we found that: i) breast cancer cell lines consistently express CSF-1 and CSF-1R; ii) the CSF-1/CSF-1R pair sustains the proliferation of breast cancer cell lines; iii) ERK1/2 is downstream CSF-1R in proliferating breast cancer cells." (PMID 22096574, 2011). "CSF-1R sustains breast cancer cells proliferation, as highlighted in two cell lines of different molecular subtypes." (PMID 22096574, 2011). "The relevance of ERK1/2 in CSF-1R signaling was highlighted by the fact that enhancement of ERK1/2 phosphorylation upon CSF-1 treatment was found in 10 out of 17 breast cancer cell lines." (PMID 22096574, 2011). "Our data are in line with previous studies in which breast cancer cell lines expressing ectopic CSF-1R showed increased expression of cyclin D1 as a consequence of ERK1/2 activation upon CSF-1 administration." (PMID 22096574, 2011). "The wide expression of CSF-1/CSF-1R pair across breast cancer cell subtypes supports CSF-1/CSF-1R targeting in breast cancer therapy." (PMID 22096574, 2011). "The role of CSF-1/CSF-1R in the proliferation of breast cancer cells was then studied in MDAMB468 and SKBR3 cells belonging to different subtypes." (PMID 22096574, 2011). "The expression of CSF-1R and/or CSF-1 strongly correlates with poor prognosis in several human epithelial tumors, including breast carcinomas." (PMID 22096574, 2011). "The expression of CSF-1R and/or CSF-1 in human breast carcinomas has been documented in both cell lines and tumors samples." (PMID 22096574, 2011). "Therapeutic strategies targeting TAMs in breast cancer have evolved from depletion approaches (CSF1/CSF1R blockade) to inhibition of monocyte recruitment (CCL2/CCR2 axis), functional reprogramming (CD40 agonism, PI3Kγ inhibition), and macrophage-directed checkpoint modulation (CD47-SIRPα axis)." (PMID 42122206, 2026). "For instance, a phase Ib/II study evaluating the combination of the CSF-1R inhibitor, pexidartinib, with pembrolizumab in advanced solid tumors, including HR+ breast cancer, demonstrated enhanced T-cell infiltration and a partial response in a subset of patients." (PMID 40566067, 2025). "Of note, repolarizing CX3CR1+ TAMs toward an immunostimulatory configuration with a monoclonal antibody targeting colony stimulating factor 1 receptor (CSF1R) ameliorated the activity of P+T against M/D-driven mammary carcinoma, to a magnitude similar to IL17A neutralization." (PMID 40662849, 2025). "Indeed, a correlation between increased circulating CSF-1 and enhanced CSF-1R+ TAMs was observed in breast cancer." (PMID 38254773, 2024). "But the results are contradictory; in a recent breast cancer clinical trial, the use of neutralizing anti-CSF1R and anti-CSF1 antibodies, along with the small-molecule inhibitors of CSF1R, showed an enhancement in the metastasis without altering primary tumor growth." (PMID 37279073, 2023). "A previous analysis of the downstream substrates of CSF-1R in breast cancer cells has unveiled novel CSF-1R targets, which could then play a specific role in epithelial tumorigenesis." (PMID 36555673, 2022).
breast cancer (continued). "PAS1 indirectly suppresses CSF-1R mRNA by interacting with vigilin, suggesting that CSF-1R mRNA may also be a target of the PAS1-vigilin complex in breast cancer." (PMID 35307730, 2022). "Moreover, CSF1 (and CSF1R) expression has been shown to correlate with progression and clinical outcome in breast cancer, making this enhancer an interesting candidate for further study." (PMID 35406623, 2022). "CSF-1R therapy in cancer seems to have mostly a synergistic effect and improve other treatments, such as adoptive cell transfer immuno-therapy or platinum-based chemotherapy in breast cancer models." (PMID 34950148, 2021). "A lack of clinical response could be explained by a preclinical study where TNBC-like 4T1 mammary tumors were treated with several anti-M-CSF/CSF1R therapies." (PMID 34832904, 2021). "Furthermore, the abundance of M-CSF1 and its receptor (CSF-1R) expressed on TAMs has been correlated to poor clinical outcomes in breast cancer." (PMID 34899721, 2021). "Studying CSF1R-targeting antibody biodistribution in humans may support elucidating the role of CSF1R-positive macrophages in healthy tissues as well as breast cancer treatment and optimizing (combination) targeting strategies." (PMID 34976826, 2021). "In conclusion, this study documents a formerly unknown role of IL-34 in human breast cancer tumorigenesis and epithelial cell transformation through its interaction with CSF1R." (PMID 33800170, 2021). "In breast cancer, colon cancer, and melanoma, inhibition of CSF-1/CSF-1R signaling using an anti-CSF-1R antibody can regulate both the number and the function of MDSCs, induce antitumor T-cell responses and tumor regression when combined with CTLA-4 blockade therapy." (PMID 35003065, 2021). "Interestingly, the synthetic (±)-kusunokinin inhibits the proliferation of breast cancer cells through the binding and the suppression of CSF1R, which consequently decreases AKT and the downstream proteins in cell proliferation (CyclinD1 and CDK)." (PMID 34361688, 2021). "While results from trials testing combined targeting of PD-1/LI and CSF-1R are still pending, promising efficacy signals of CSF-1R inhibitors have been demonstrated in combination with chemotherapy in solid organ malignancies, including breast cancer." (PMID 34830923, 2021). "Overall, our study highlights the previously unknown role of IL-34/CSF1R signaling in breast cancer and demonstrates the regulatory role of PIN1 in IL-34-induced tumorigenesis." (PMID 33800170, 2021). "For example, in a murine breast cancer model, local pulmonary administration of CSF-1R inhibition allowed the drug to overcome lung physiological barriers of administration better than oral administration, significantly enhancing the M1/M2 ratio at a much lower dose." (PMID 33968034, 2021). "Findings from our exploratory analyses showing a negative association of CSF-1R+ carcinoma cells even in immune-rich ER-positive breast cancers require validation in independent clinical cohorts." (PMID 34830923, 2021). "Studies with CSF-1R signaling antagonists, combined with the drug paclitaxel or carboplatin, showed enhanced tumor control and reduced metastasis in preclinical models of breast cancer." (PMID 33968034, 2021). "Also, importantly, in preclinical breast cancer models, when macrophages are depleted using anti-CSF-1R therapy or their phenotype was converted to an anti-tumor phenotype, anti-PD-1 therapy induced potent anti-tumor immunity." (PMID 33968034, 2021). "In addition, anti-CD115 antibody (CSF-1R antibody) treatment depletes TAMs decreasing bone lesions in a breast cancer mouse model." (PMID 32326073, 2020). "In sum we identified iron deposition as a metabolic biomarker of macrophage infiltration in murine and human breast cancer that identifies responsive polarized TAM populations to CSF1R immunotherapy using histological and in vivo iron imaging together with preclinical cancer research approaches." (PMID 30696910, 2019).
breast cancer (continued). "The function of CSF1/CSF-1R remains controversial also in experimental models of breast cancer." (PMID 31406165, 2019). "CSF-1 can also colocalize with CSF-1R in the nucleus in breast cancer cells." (PMID 31565097, 2019). "CSF-1R itself was shown to be recruited to specific genes in breast cancer cells." (PMID 31028249, 2019). "The eventual clinical translation of iron as a metabolic biomarker for macrophage detection and its combination with CSF1R immunotherapy largely depends on whether iron deposits are detectable in human breast cancer." (PMID 30696910, 2019). "However, while the role of CSF-1/CSF-1R has been extensively studied in breast cancer, the implication of IL-34 in breast cancer formation and progression is still poorly understood." (PMID 29796177, 2018). "Moreover, enforced NF-κB activation in myeloid cells through inducible overexpression of Ikkβ under the control of the Csf1r promoter inhibited experimental colonization of lungs with breast cancer cells." (PMID 29682184, 2018). "Together with the observed low CSF-1R activation in breast cancer cells, we hypothesize that IL-34 and its receptor PTPRZ1 directly regulate cancer cells, whereas CSF-1/CSF-1R are primarily involved in regulation of stromal and immune cells." (PMID 29796177, 2018). "Using CSF1R inhibitors to effectively deplete the TAM population in breast cancer patients could allow for improved response of metastatic lesions subsequently treated with SBRT or fractionated radiation." (PMID 29862083, 2018). "However, most of these studies reported no or low efficacy when used as monotherapy, while combination of CSF1R inhibition with standard of care (e.g., chemotherapy or irradiation) led to synergistic anti-tumor effects in, e.g., glioma and breast cancer." (PMID 29681904, 2018). "Despite the known expression of CSF-1 and CSF-1R in human breast cancer and their clear therapeutic potential, the role of IL-34 remains unclear." (PMID 29796177, 2018). "Third, although targeting CSF1R has shown as a novel therapeutic strategy for inflammatory, autoimmune disorders and cancer, such as rheumatoid arthritis and breast cancer, a direct association between CSF1R and HCC development has not been evidenced." (PMID 30026540, 2018). "Tumor growth in this MMTV-PymT-driven mouse breast cancer was dependent on the WNT7B expression by myeloid cells since in the CSF-1R promoter dependent conditional knock-out model the myeloid selective ablation of Wnt7b reduced tumor growth beyond the failure of the angiogenic switch." (PMID 28197019, 2017). "However, in spontaneous mammary tumor model, inhibition of CSF1R resulted in similar kinetics for depletion and recovery of both M2-oriented MHC IIlo and M1-oriented MHC IIhi TAMs." (PMID 26595525, 2016). "Thus, although 5A1 did not interfere with metabolic activity, viability, migration capacity, or CSF-1R down-stream signalling, it functionally inhibited MG-induced invasiveness of human and murine breast cancer cells." (PMID 26098772, 2015). "Moreover, analysis of lung and breast cancer brain metastasis revealed significant differences of CSF-1 and CSF-1R expression." (PMID 26098772, 2015). "Furthermore, breast cancer cells are not only a source of CSF-1 as already described, but also a source for IL-34, the alternative ligand for the CSF-1R." (PMID 26098772, 2015). "Thus, we tested the gene expression of CSF-1 and CSF-1R in primary tumor samples and correlated their expression to the molecular breast cancer subtypes as well as the incidence of metastases." (PMID 26098772, 2015). "Additionally, we analyzed a subset of primary breast cancer patients, and certain patients with brain metastasis of lung and breast cancer and found high CSF-1R, CSF-1 and/or IL-34 expression, respectively." (PMID 26098772, 2015).